KCNE5 (potassium voltage-gated channel subfamily E regulatory subunit 5)
Description:
Potassium channel ancillary subunit that is essential for generation of some native K(+) currents by virtue of formation of heteromeric ion channel complex with voltage-gated potassium (Kv) channel pore-forming alpha subunits. Functions as an inhibitory beta-subunit of the repolarizing cardiac potassium ion channel KCNQ1.
Synonyms: KCNE1L
Tractability: Antibody: its Gene Ontology location is reachable by antibodies, with high confidence; UniProt predicts a signal peptide or a membrane-spanning region.
Gene: Protein-coding gene on chromosome X (109,623,700 to 109,625,172, reverse strand). Ensembl gene ENSG00000176076.
Subcellular location: Membrane
Pathways (Reactome):
Muscle contraction: Phase 2 - plateau phase; Phase 3 - rapid repolarisation
Gene Ontology:
Molecular function: potassium channel regulator activity; protein binding; transmembrane transporter binding; delayed rectifier potassium channel activity; voltage-gated potassium channel activity involved in ventricular cardiac muscle cell action potential repolarization; voltage-gated potassium channel activity
Biological process: atrial cardiac muscle cell action potential; cardiac muscle contraction; negative regulation of potassium ion export across plasma membrane; negative regulation of potassium ion transmembrane transport; positive regulation of potassium ion transmembrane transport; regulation of atrial cardiac muscle cell membrane repolarization; regulation of heart contraction; regulation of heart rate by cardiac conduction; regulation of membrane repolarization; regulation of potassium ion transmembrane transport; regulation of ventricular cardiac muscle cell membrane repolarization; ventricular cardiac muscle cell action potential; membrane repolarization during action potential; potassium ion export across plasma membrane; membrane repolarization during ventricular cardiac muscle cell action potential; monoatomic ion transport
Cellular component: membrane; plasma membrane; voltage-gated potassium channel complex
Gene-disease validity (ClinGen):
ClinGen rates the evidence that KCNE5 causes each of these diseases.
Brugada syndrome (autosomal dominant): Disputed. A genetically heterogeneous condition characterized by complete or incomplete right bundle branch block accompanied by ST elevation in leads V1-V3.
Homologues: Orthologues: chimpanzee KCNE5 (98% identical), macaque KCNE5 (93% identical), rabbit KCNE5 (87% identical), pig KCNE5 (87% identical), mouse Kcne5 (81% identical), dog KCNE5 (80% identical), rat Kcne5 (80% identical). Paralogues in human: KCNE3 (22% identical).
Diseases named in the same sentence as KCNE5 in open-access papers:
KCNE5 is named in the same sentence as 21 diseases in open-access papers, as found by Europe PMC text mining. Sharing a sentence is not in itself a finding about the gene and the disease. The quoted sentences say what the papers report.
Brugada syndrome (7 papers, 2017 to 2022). "The previous studies also found a variant on the KCNJ5 (potassium voltage-gated channel subfamily E regulatory subunit 5) gene located on chromosome X in Japanese patients with Brugada syndrome." (PMID 36617651, 2022). "Human KCNE5 mutations are associated with atrial fibrillation and Brugada syndrome, and they may predispose to cardiac arrhythmias." (PMID 34368133, 2021).
atrial fibrillation (4 papers, 2011 to 2021). A disorder characterized by an electrocardiographic finding of a supraventricular arrhythmia characterized by the replacement of consistent P waves by rapid oscillations or fibrillatory waves that vary in size, shape and timing and are accompanied by an irregular ventricular response. "Some of the identified variants have previously been associated with arrhythmia, i.e. p.S38G in KCNE1 and p.P33S in KCNE5, that are known polymorphisms associated with increased risk of atrial fibrillation." (PMID 21967835, 2011).
cardiac arrhythmia (3 papers, 2011 to 2024). Any disturbances of the normal rhythmic beating of the heart or MYOCARDIAL CONTRACTION. "Male, but not female, CIH rats have altered expression of Cav3, Cacna1c, Cacnb2, Kcne5, Kcnd2, and Hcn2 which may preferentially predispose postnatal males to develop arrhythmia." (PMID 38981849, 2024).
cognitive decline (1 paper, 2025). "Therefore, the downregulation of VGF, NEUROD6, KCNF1, KCNE5, CRH, and RPH3A may contribute to the cognitive decline observed in elderly individuals with AD." (PMID 39834440, 2025).
dementia (1 paper, 2018). Loss of intellectual abilities interfering with an individual's social and occupational functions. "This study is the first to identify a cerebral artery‐specific impairment of Kv7 channel function in a tauopathy‐associated dementia mouse model and we suggest this functional attenuation might be due to a downregulation of the ancillary subunit, KCNE5 in the cerebral arteries of the rTg4510 mice." (PMID 30548427, 2018).
idiopathic ventricular fibrillation (1 paper, 2022). "In addition to KCNE3, KCND3 can be assembled with multiple KCNE subunits, of which KCNE5 can regulate Ito, showing a correlation with BrS and idiopathic ventricular fibrillation." (PMID 35783865, 2022).
heart disease (1 paper, 2020). "KCNE5 (potassium voltage-gated channel subfamily E regulatory subunit 5) was more closely related to heart disease." (PMID 33043022, 2020).
KCNE5 also shares sentences with these, for which no sentence is quoted: Arrhythmia (2 papers); Alport syndrome (1); Alström syndrome (1); cardiovascular disease (1); elliptocytosis (1); hearing loss (1); Jensen syndrome (1); long QT syndrome (1); mental retardation (1); neurodegenerative disease (1); Obesity (1); tauopathy (1); type 2 diabetes mellitus (1); ventricular tachycardia (1).